PVRIG (PVR related immunoglobulin domain containing)
Diseases named in the same sentence as PVRIG in open-access papers (continued):
Sharing a sentence is not in itself a finding about the gene and the disease.
tumor (continued). "Moreover, PVRIG blockade has been shown to reduce the tumor burden in a mouse model." (PMID 38554184, 2024). "Indeed, blocking human PVRIG in tumor-bearing humanized mice resulted in smaller tumor sizes, indicating the therapeutic value of anti-hPVRIG mAb, meanwhile, pointing out that anti-hPVRIG mAb could be effective by acting only on NK cells." (PMID 34174928, 2021). "Furthermore, by constructing MC38 tumor model using Rag1−/− mice (which lack T cells and B cells), we showed that anti-PVRIG mAb was effective even in the absence of adaptive immunity, suggesting the importance of NK cells in PVRIG-targeted treatments." (PMID 34174928, 2021). "However, both early (when tumor size is around 10 mm3) and late (when tumor size is around 100–150 mm3) treatments with our anti-PVRIG mAb alone were effective against MC38 tumors in vivo, resulting in significant inhibition of tumor growth and prolonged survival of tumor-bearing mice." (PMID 34174928, 2021). "Consistent with our results in Rag1−/− mice, we observed significantly slower tumor growth (P < 0.05) in humanized tumor-bearing mice treated with anti-hPVRIG mAb compared to those treated with control antibody, indicating that PVRIG blockade in humanized mice could benefit directly via NK cells." (PMID 34174928, 2021). "In conclusion at least one target molecule of the TIGIT/PVRIG pathway axis or the CD39/CD73 purinergic pathway was more frequently and at a higher MFI expressed in each tumor entity (BC: PVRIG, CD73; PC: TIGIT, CD39; NSCLC: CD73; MM: TIGIT, PVRIG, CD39)." (PMID 40274631, 2025). "TIGIT, CD226, CD96 and PVRIG are expressed on T and NK cells, whereas CD155 (PVR) is often overexpressed on tumour cells." (PMID 41462864, 2025). "Together, TIGIT/PVRIG—CD112/CD155/PVRL4 signaling has recently shown to prevent T cell proliferation, tumor cell lysis, and the production of proinflammatory cytokines." (PMID 40274631, 2025). "TIGIT was aberrantly co-expressed with PVRIG (4 of 4 tumor entities) and CD39 (2 of 4 tumor entities)." (PMID 40274631, 2025). "While comparing between matched and unmatched tumour and normal tissue samples, upregulation of checkpoint receptor genes, notably CD47, CTLA4, HAVCR2, PVRIG, SIGLEC7, and SIGLEC9, were specifically detected in malignant compared to normal tissues." (PMID 39877370, 2024). "The binding of PVRL2 to PVRIG or PVRL2 to TIGIT suppresses tumor immunity, whereas the binding of PVRL2 to DNAM1 promotes tumor immunity." (PMID 39156900, 2024). "PVRIG belongs to the family of inhibitory receptors and is also expressed on CD8 T cells, but inhibition of PVRIG has been shown to promote anti-tumor immunity of NK cells in mice and humans." (PMID 37874153, 2023). "Innate ICIs achieve anti-tumor purposes by targeting checkpoints such as SIRPα, TIGIT, PVRIG, LILRB2, NKG2A, LAG-3, TIM-3, VISTA and CD32B." (PMID 37510993, 2023). "The co-inhibitory receptors CD96, TIGIT, PVRIG and the costimulatory receptor CD226 comprise a critical regulatory system for lymphocyte activity and anti-tumor immunity, and they share the same ligands CD155 and PVRL2." (PMID 34174928, 2021). "More importantly, anti-PVRIG treatment also increased the number of NK cells and CD8+ T cells infiltrated into the tumor." (PMID 34174928, 2021). "PVRL2 (CD112), known as the ligand of PVRIG and CD226, is overexpressed in different types of tumor cell and plays an immunosuppressive role in T cell function." (PMID 33747255, 2021). "Engagement of CD226 with its ligands PVRL2 and CD155 on target cells is essential for enhancing the anti-viral and anti-tumor functions of NK cells and T cells, whereas CD96, TIGIT and PVRIG counterbalance CD226-dependent lymphocyte activation." (PMID 34174928, 2021). "To further asses the importance of NK cells in PVRIG blockade, we used Rag1−/− mice (which lack both T cells and B cells) to construct the MC38 subcutaneous tumor model." (PMID 34174928, 2021).
tumor (continued). "Whereas DNAM-1 is an activating/co-stimulatory receptor involved in recognition and lysis of tumor cells, TIGIT and PVRIG engagement inhibit NK cell function." (PMID 31234588, 2019). "The high expression of NECTIN-2, the ligand of PVRIG, which has also been reported by others in HCC tumors, might bridle anti-tumor response efficiency." (PMID 36672396, 2023). "Similar to TIGIT, PVRIG, presented on NK cells and CD8+ T cells, is a suppressible receptor that could identify CD112 on tumor cells." (PMID 37510993, 2023). "Despite lack of induction on in vitro-activated NK cells, increased PVRIG expression is observed on tumor-infiltrating NK cells." (PMID 35812451, 2022). "Moreover, genetic- or biologics-based co-blockade of TIGIT and CD96 has been shown to improve tumor control while co-blockade of TIGIT and PVRIG has also been shown to promote NK cell function." (PMID 35812451, 2022). "Indeed, blockade of PVRIG restores the proliferation and cytokine production of T cells, and genetic deletion of PVRIG enhances IFN-γ production of tumor-infiltrating CD8+ T cell and slows the tumor growth." (PMID 34174928, 2021). "One hypothesis might be that the PVRIG/NECTIN-2 axis is a new negative feedback loop, either proper to the tumor liver microenvironment or associated with a specific context of immune response." (PMID 36672396, 2023). "Genetic knock-out of PVRIG or pharmacologic blockade of PVRIG/PVRL2 interaction significantly inhibited the exhaustion of NK cells and enhanced their cytotoxicity and IFN-γ production and therefore limited the subcutaneous tumor growth and prolonged the survival of tumor-bearing mice." (PMID 34174928, 2021). "In addition, tumor-bearing mice treated with anti-PVRIG mAb showed lower frequency of tumor-infiltrating CD8+ T cells expressing inhibitory receptor CD96 and higher frequency of tumor-infiltrating CD8+ T cells expressing NKG2D, TRAIL, CD107a, GzmB and IFN-γ." (PMID 34174928, 2021). "In addition, we systemically characterized the mechanism by which PVRIG blockade induces tumor killing via NK cell activation rather than T-cell activation and show that the effector function of competent Fc is necessary for the antitumor efficacy of PVRIG blockade in preclinical models." (PMID 38554184, 2024). "However, the role of PVRIG on NK cells in tumor microenvironment has not been investigated." (PMID 34174928, 2021). "They receive an activation signal and become activated, but they also receive negative signals from PVRIG, which is strongly engaged with NECTIN-2, which might limit anti-tumor activation." (PMID 36672396, 2023).
cancer (15 papers, 2019 to 2024). A tumor composed of atypical neoplastic, often pleomorphic cells that invade other tissues. "PVRL2, the only ligand of PVRIG, is highly expressed in multiple cancer types and has been associated with poor survival." (PMID 38554184, 2024). "To explore the role of PVRIG in cancer, we analyzed the associations between PVRIG expression and various molecular and clinical features in 33 TCGA cancer types, including stemness, immune, and survival prognosis." (PMID 37542274, 2023). "PVRIG abundance is a risk factor for AD but a protective factor for cancer." (PMID 37542274, 2023). "PVRIG has also been shown to be expressed in certain types of cancer, and the highest expression levels in terms of cancer tissues have been reported in kidney, ovary, lung, prostate, and endometrium." (PMID 38638433, 2024). "Poliovirus receptor-related immunoglobulin domain-containing protein, or PVRIG, is a newly discovered immune checkpoint that has emerged as a promising target for cancer immunotherapy." (PMID 38554184, 2024). "In pan-cancer and in 30 individual cancer types, PVRIG expression was positively correlated with the enrichment scores of TILs (FDR < 0.05)." (PMID 37542274, 2023). "PVRIG expression was significantly and positively correlated with the apoptosis pathway’s enrichment scores in pan-cancer and in 26 individual cancer types (FDR < 0.05)." (PMID 37542274, 2023). "Recently, it has been shown that nectin-2 protein overexpressed in cancer cells functions as an immune checkpoint by binding to the nectin-2 protein receptor (PVRIG) of NK and cytotoxic T cells." (PMID 36293219, 2022). "This review provides an overview of the CD226 axis in the context of cancer, with a focus on the status of immunotherapeutic strategies (TIGIT, CD96, and PVRIG) and their underlying biology (i.e., cis/trans interactions)." (PMID 35812451, 2022). "Interestingly, in a few cancer types, such as LGG, GBM, and DLBC, the association between PVRIG expression and the molecular features showed different results with most of the other cancer types." (PMID 37542274, 2023). "Moreover, PVRIG had a significant positive expression correlation with the ratios of CD8+/CD4+ regulatory T cells in pan-cancer and in 29 individual cancer types (Pearson correlation, FDR < 0.05)." (PMID 37542274, 2023). "Immune-checkpoint inhibitors targeting the PVRIG-Nectin-2 axis in Nectin-2 positive cancers may be evaluated as potential drugs." (PMID 36553083, 2022). "Overall, it can be speculated that in cancer patients the TIGIT/PVRIG pathways are upregulated and represent novel targets for checkpoint blockade immunotherapy." (PMID 31234588, 2019). "It suggests that PVRIG could be an important bridge linking AD and cancer." (PMID 37542274, 2023). "PVRL2 is overexpressed in multiple types of cancers, and the blockage of PVRL2 and PVRIG genes increases T-cell function." (PMID 37779898, 2023). "PVRIG is a co-inhibitory receptor of the DNAM/TIGIT/CD96 family and binds to PVRL2, both abnormally expressed in human cancers." (PMID 35641998, 2022). "By virtue of the clinical progression of TIGIT antagonists and emergence of novel CD96- and PVRIG-based approaches, our overall understanding of the ‘CD226 axis’ in cancer immunotherapy is starting to take shape." (PMID 35812451, 2022). "TIGIT could enhance T-cell function by inhibiting PVRIG, so TIGIT-PVRIG pathways play a vital role in human cancers." (PMID 34901000, 2021). "Previous study has reported positive detection of PVRIG on both T cells and NK cells from healthy peripheral blood and various human cancer tissues; however, the expression of PVRIG on murine NK cells has not been fully revealed." (PMID 34174928, 2021). "The axis of DNAM-1 and TIGIT/PVRIG/TACTILE, in which shared ligands and different receptor-ligands affinities regulate the immune response, represents a novel checkpoint for improving immune responses against cancer." (PMID 31234588, 2019).
cancer (continued). "Transcriptomic analysis showed that PVRIG expression had significant negative correlations with stemness scores, and positive correlations with antitumor immune responses and overall survival in pan-cancer and multiple cancer types." (PMID 37542274, 2023). "Notably, PVRIG displayed significant negative expression correlations with stemness scores in pan-cancer and in 30 individual cancer types (Spearman correlation, FDR < 0.05)." (PMID 37542274, 2023).
PVRIG also shares sentences with these, for which no sentence is quoted: acute leukemia (1 paper); Anorexia (1); Cachexia (1); chronic GVHD (1); colon adenocarcinoma (1); coronary heart disease (1); COVID-19 (1); diabetes (1); endometrial cancer (1); fibrosarcoma (1); hepatocellular carcinoma (1); lipoma (1); lung carcinoma (1); melanoma (1); pancreatic cancer (1); prostate carcinoma (1).